TIMM29 (translocase of inner mitochondrial membrane 29)
Description:
Component of the TIM22 complex, a complex that mediates the import and insertion of multi-pass transmembrane proteins into the mitochondrial inner membrane. The TIM22 complex forms a twin-pore translocase that uses the membrane potential as the external driving force. Required for the stability of the TIM22 complex and functions in the assembly of the TIMM22 protein into the TIM22 complex. May facilitate cooperation between TIM22 and TOM complexes by interacting with TOMM40.
Synonyms: TIM29; c19orf52
Tractability: Small molecule: a structure with a bound ligand is known. Antibody: UniProt predicts a signal peptide or a membrane-spanning region. PROTAC: ubiquitination databases record sites on it.
Gene: Protein-coding gene on chromosome 19 (10,928,811 to 10,933,535, forward strand). Ensembl gene ENSG00000142444.
Subcellular location: Mitochondrion inner membrane
Subcellular location (Human Protein Atlas): Mitochondria; Nucleoplasm
Gene Ontology:
Molecular function: protein binding; protein-macromolecule adaptor activity
Biological process: protein insertion into mitochondrial inner membrane
Cellular component: mitochondrial inner membrane; mitochondrial intermembrane space; mitochondrion; TIM22 mitochondrial import inner membrane insertion complex
Genetic constraint (gnomAD): Loss-of-function variants: 24 observed, 15.77 expected, observed/expected ratio (o/e) 1.52, 90% interval 1.09 to 1.92. The synonymous counts are far from expectation, so gnomAD's model fits this gene poorly and the ratio says little. Missense variants: 404 observed, 319.13 expected, observed/expected ratio (o/e) 1.27, 90% interval 1.17 to 1.38. Synonymous variants: 209 observed, 148.43 expected, observed/expected ratio (o/e) 1.41, 90% interval 1.26 to 1.58.
Homologues: Orthologues: chimpanzee TIMM29 (99% identical), macaque TIMM29 (98% identical), pig TIMM29 (87% identical), guinea pig TIMM29 (84% identical), dog TIMM29 (84% identical), rat Timm29 (83% identical), mouse Timm29 (81% identical), rabbit TIMM29 (81% identical), tropical clawed frog timm29 (45% identical), zebrafish timm29 (40% identical), Caenorhabditis elegans R04F11.5 (18% identical), Drosophila melanogaster CG14270 (18% identical).
Diseases named in the same sentence as TIMM29 in open-access papers:
TIMM29 is named in the same sentence as 1 disease in open-access papers, as found by Europe PMC text mining. Sharing a sentence is not in itself a finding about the gene and the disease.
TIMM29 shares sentences with these, for which no sentence is quoted: hepatocellular carcinoma (1 paper).